RN7SL703P (RNA, 7SL, cytoplasmic 703, pseudogene)
Gene: Miscellaneous RNA gene on chromosome 3 (181,813,401 to 181,813,702, forward strand). Ensembl gene ENSG00000266317.
Homologues: Orthologues: chimpanzee Metazoa_SRP (99% identical), macaque Metazoa_SRP (91% identical). Paralogues in human: RN7SL1 (79% identical), RN7SL2 (79% identical), RN7SL3 (79% identical), RN7SL478P (79% identical), RN7SL126P (78% identical), RN7SL220P (78% identical), RN7SL556P (78% identical), RN7SL566P (78% identical), RN7SL300P (78% identical), RN7SL655P (78% identical), RN7SL296P (77% identical), RN7SL797P (77% identical), and 701 more.